ALB (albumin)
Diseases named in the same sentence as ALB in open-access papers (continued):
Sharing a sentence is not in itself a finding about the gene and the disease.
anaphylaxis (27 papers, 1997 to 2025). An acute hypersensitivity reaction that occurs from exposure to an allergen. "Gelatin carries the highest incidence of anaphylaxis and is more likely to cause anaphylaxis than albumin and other colloids, Allergic reactions to gelatin colloids occur with symptoms of anaphylaxis, sneezing, bronchospasm, and urticaria." (PMID 40476920, 2023). "Some case reports revealed that bovine serum albumin (BSA) may be a causative agent in anaphylaxis, even severe, after standard intrauterine insemination or in vitro fertilization, when added to the culture medium of spermatozoids." (PMID 34575019, 2021). "All four groups of wheat allergens (gliadins, glutenin, albumin, and globulin) exhibit intrinsic allergenicity and anaphylaxis-eliciting properties." (PMID 40077585, 2025). "This syndrome manifests as a broad spectrum of allergic reactions (from mild urticaria to severe anaphylaxis) after consuming pork meat in subjects that are sensitized to cat serum albumin." (PMID 40739451, 2025). "Diagnosing the cause of anaphylaxis, positive results from SPT and sIgE have been obtained from semen culture, albumin extracts, and sera from pig, horse, cat, dog, and bovine origin." (PMID 40739451, 2025). "A decrease in serum protein and human serum albumin levels has been noted during anaphylaxis and can be used as indirect measurements of extravasation in the human body and of anaphylaxis severity." (PMID 41016999, 2025). "Mouse model of atopic dermatitis (AD) induced by 2, 4,-dinitroflurobenzene (DNFB) and anaphylaxis employing 2,4-dinitropheny-human serum albumin (DNP-HSA) were used to examine the role of HHT in allergic inflammations." (PMID 32733254, 2020). "Active anaphylaxis induced by triple antigen alongside bovine serum albumin (BSA) is a key model to study the symptomatic effect of type I allergy." (PMID 30863445, 2019). "Since very small amounts of bovine serum albumin is present in many vaccines including the MMR, such ingredients in vaccines are likely to cause anaphylaxis in those who are sensitized to beef." (PMID 30455720, 2018). "The majority of cases of vaccine associated anaphylaxis were due to the measles, mumps and rubella (MMR) vaccine, which contains bovine serum albumin." (PMID 30455720, 2018). "An increased basal production of NO was observed in cells taken after anaphylaxis, associated with a reduced response to platelet-activating factor, interleukin 1beta, and IgE/DNP-bovine serum albumin complexes." (PMID 18472830, 1997). "Although this study used trinitrophenol (TNP)-specific IgE and TNP-ova albumin protein as a model allergen, these bindings may be relevant for wheat anaphylaxis, although this needs to be confirmed." (PMID 40077585, 2025). "In the future, our studies will focus on the development of new stabilizer formulations without human blood albumin and gelatin, which caused anaphylaxis symptoms in systemic anaphylaxis experimental guinea pigs." (PMID 40872963, 2025). "It is important to note that albumin is a blood-derived product and may lead to allergic reactions, anaphylaxis, and the transmission of viral or unidentified diseases." (PMID 39338169, 2024). "One patient developed anaphylaxis to FFP requiring a change of exchange fluid to albumin." (PMID 39722810, 2024). "The higher adverse events rate in previous canine and human VIT studies as compared to our study can be explained by the fact that these studies used human serum albumin alongside the allergen extracts, which may act as a sensitizer and induce anaphylaxis." (PMID 37835609, 2023). "The preferred technique is a 1-day protocol using lower doses of 99mTc-labeled albumin nanocolloid without lymphazurin blue dye, which carries a risk for anaphylaxis." (PMID 32025953, 2020). "The presence of endotoxins, polymers, bradykinin and other proteins may alter the quality of the albumin and result in anaphylaxis." (PMID 21181070, 2010).
anaphylaxis (continued). "Topical application of CYM was effective against immunoglobulin E (IgE)/dinitrophenyl-conjugated bovine serum albumin- (DNP-BSA-) induced degranulation of RBL-2H3 cells and anaphylaxis in ICR mice." (PMID 26981139, 2016). "In the present study, we investigated the antiallergic effects of eckol isolated from the marine brown algae, Ecklonia cava using immunoglobulin E (IgE)/bovine serum albumin (BSA)-stimulated mouse bone marrow-derived cultured mast cells (BMCMC) and a mouse model of anaphylaxis." (PMID 32397556, 2020). "The present study investigates the anti-allergic effect of an ethanol extract from S. horneri (SHE) on immunoglobulin E (IgE)/bovine serum albumin (BSA)-mediated activation in bone marrow-derived cultured-mast cells (BMCMCs) and passive cutaneous anaphylaxis (PCA) reaction in mice." (PMID 33256200, 2020). "Passive systemic anaphylaxis was elicited by injecting of 10 μg anti-DNP IgE intravenously, 24 hrs later, mice were administrated with DNP-human serum albumin (DNP-HSA) antigen by intravenously injection, and then core body temperature was monitored at indicated time intervals." (PMID 24834318, 2014). "Indeed, albumin represents an attractive colloid in hepatic resection because of the maintenance of osmotic pressure, absence of anaphylaxis and side effect, safety (absence of nephrotoxicity), and effectiveness (reduction of renal morbidity among cirrhotic)." (PMID 40551534, 2025). "Rarely, symptoms resembling anaphylaxis, such as flushing, hypotension, abdominal cramping, and other gastrointestinal symptoms, have been reported in patients who had taken an ACE inhibitor within 24 to 30 h of plasmapheresis and were receiving albumin for fluid replacement." (PMID 38138254, 2023).
hyperphosphatemia (27 papers, 2008 to 2026). Abnormally high level of phosphate in the blood. "Dialysis vintage, dialysis exchanges, urine output, serum albumin, serum creatinine, hyperphosphatemia knowledge behavior, and social support were the associated factors of hyperphosphatemia in CAPD patients." (PMID 37122336, 2023). "In the multivariate analysis focusing on biochemical parameters (“Biochemical” model), a high eGFR at DI, hyperphosphatemia (> 2.0 mmol/L), low serum albumin (< 33 g/L), and elevated CRP (> 10 mg/L) associated independently with mortality." (PMID 35761193, 2022). "Similar to these studies, we found that hyperphosphatemia was positively associated with nPCR and the albumin and transferrin levels and negatively associated with age and PD adequacy." (PMID 26187601, 2015). "Multivariate linear regression revealed that hyperphosphatemia was associated with elevations in the transferrin and serum albumin levels and normalized protein catabolic rate (nPCR) and reductions in the hemoglobin level, residual Ccr, and PD Ccr." (PMID 26187601, 2015). "After adjusting for sex, serum albumin and hemoglobin, age, dialysis patterns and region of residency were still independently associated with hyperphosphatemia." (PMID 22994525, 2012). "Of relevance, increasing hyperphosphatemia in CKD is also associated with declining serum albumin levels, implying that hyperphosphatemia may also be positively associated with periodontal disease severity." (PMID 30754693, 2019). "Other factors found to be independently associated with hyperphosphatemia were elevations in the transferrin (p = 0.007) and serum albumin levels (p = 0.049) and nPCR (p < 0.001) and decreases in the hemoglobin level (p = 0.015), residual Ccr (p < 0.001), and PD Ccr (p < 0.001)." (PMID 26187601, 2015). "In bivariate analysis, risk factors for hyperphosphatemia included higher levels of albumin (p < 0.01), higher vitamin D (p = 0.01), lower parathyroid hormone (p = 0.02), higher corrected calcium (< 0.01), lower fasting glucose (< 0.01) and lower hemoglobin levels (p = 0.03)." (PMID 23965134, 2013). "Regarding the relationship between phosphorus and BMI, studies have shown that patients with hyperphosphatemia have higher albumin levels and higher protein intake, as well as a higher BMI." (PMID 39388423, 2024). "Dialysis vintage, dialysis exchanges, urine output, serum albumin, serum creatinine, hyperphosphatemia knowledge behavior level, and social support level were the associated factors of hyperphosphatemia in CAPD patients." (PMID 37122336, 2023). "Independent factors predicting death were high age, comorbidity, clinical contraindications to PD or HD, suboptimal DI, high eGFR, low serum albumin, hyperphosphatemia, high C-reactive protein, signs of overhydration and cerebral symptoms at DI." (PMID 35761193, 2022). "As a result, hyperphosphatemia was more common in rural patients even if albumin levels and nPCR were not significantly different between the two groups." (PMID 25880687, 2015). "The prevalence and severity of albuminuria (p<0.0003), hyperphosphatemia (p<.0001), hyperparathyroidism (p<0.0001), and metabolic acidosis (p<0.0009) increased with decreasing eGFR, whereas serum albumin, 25OHD, and CRP were not statistically significantly associated with renal function." (PMID 25659076, 2015).
kidney stones (27 papers, 2018 to 2026). "Nutritional deficiencies lead to reduced albumin levels and impaired immune function, decreasing lymphocyte counts and potentially increasing the risk of kidney stones." (PMID 39964992, 2025). "This was associated with an increase in the uric acid level, serum albumin, and deposition of urate crystals in soft tissue and kidney stones." (PMID 40867880, 2025). "Our research indicates a potential association between higher serum albumin levels and a reduced prevalence of kidney stones, though the direct relationship remains somewhat elusive." (PMID 39574520, 2024). "On the other hand, serum albumin concentrations exhibited a linear association with the prevalence of kidney stones." (PMID 39570091, 2024). "Low albumin levels have been associated with poor nutritional status and systemic inflammation, both of which are risk factors for kidney stone formation." (PMID 39570091, 2024). "Therefore, a decrease in albumin levels reduces the body’s ability to resist oxidative stress, potentially exacerbating the risk of kidney stone formation." (PMID 40729360, 2025). "Inflammatory conditions that reduce serum albumin may, therefore, enhance the urinary excretion of free calcium and other stone‐promoting substances, increasing the risk of kidney stone formation." (PMID 39570091, 2024). "The KDIGO guideline recommends screening individuals at risk for CKD, including those with CAKUT, recurrent kidney stones, and known genetic variants associated with CKD, through both urine albumin measurement and GFR assessment." (PMID 40437108, 2025). "Mediation analysis identified albumin (ALB) and red cell distribution width (RDW) as partial mediators in the association between IR and kidney stones." (PMID 40729360, 2025). "Multiple logistic regressions and restricted cubic spline (RCS) regression were applied to examine the associations between RDW, albumin, RAR, and the prevalence of kidney stones." (PMID 39570091, 2024). "Multiple logistic regression associations of continuous red blood cell distribution width to albumin ratio (RAR) with the prevalence of kidney stones among the general adult population in NHANES 2007–2018." (PMID 39570091, 2024). "By considering both RDW and serum albumin levels, we captured the complex interplay between inflammation, erythrocyte dynamics, and kidney stone prevalence." (PMID 39570091, 2024). "Multiple logistic regression associations of quartiles of red blood cell distribution width to albumin ratio (RAR) with the prevalence of kidney stones among the general adult population in NHANES 2007–2018." (PMID 39570091, 2024). "Stratified analyses of the associations between quartiles of red blood cell distribution width to albumin ratio (RAR) with the prevalence of kidney stones among the general adult population in NHANES 2007–2018." (PMID 39570091, 2024). "These markers are positively correlated with the prevalence of kidney stones, suggesting an indirect link between low albumin levels and stone formation." (PMID 39574520, 2024). "Noteworthy, the reported inhibitory effects of human albumin on kidney stone formation rely on a different mechanism, which favors generation of di- and trihydrate forms of calcium oxalate crystals." (PMID 30319631, 2018). "Low albumin levels increase oxidative stress, a major contributor to kidney stone formation." (PMID 39964992, 2025). "Accordingly, this study investigates the association between eGDR and kidney stones among non-diabetic U.S. adults and explores the potential mediating roles of ALB and RDW in this relationship." (PMID 40729360, 2025). "Conversely, there was a linear and negative association between albumin and kidney stone prevalence (P for nonlinearity = 0.499)." (PMID 39570091, 2024). "We analyzed the RDW, albumin, and RAR levels obtained from the National Health and Nutrition Examination Survey (NHANES) to investigate the association between RAR levels and the prevalence of kidney stones." (PMID 39570091, 2024).
kidney stones (continued). "In model 3, continuous RDW (OR = 1.09 [1.04–1.13], p < 0.001) and RAR (OR = 1.31 [1.16–1.47], p < 0.001) remained positively correlated with kidney stone prevalence, whereas continuous albumin (OR = 0.71 [0.59–0.87], p < 0.001) exhibited the opposite association." (PMID 39570091, 2024). "Conversely, albumin (OR = 0.75 [0.63–0.89], Ptrend < 0.001) exhibited a significant negative association with kidney stone prevalence." (PMID 39570091, 2024). "Conversely, there was a linear negative association between albumin levels and the prevalence of kidney stones." (PMID 39570091, 2024). "As albumin levels increased, the OR values for kidney stone prevalence consistently decreased." (PMID 39570091, 2024). "In the unadjusted model, both continuous RDW and RAR showed positive associations with kidney stone prevalence, while continuous albumin displayed a negative association." (PMID 39570091, 2024). "In our cohort of patients, the main indications for switching to hormone replacement therapy were: inadequate control of albumin-adjusted total serum calcium level despite conventional treatment, kidney stones, and/or gastrointestinal intolerance to supplementation calcium/malabsorption." (PMID 35460461, 2022). "Additionally, the relationship between IR and kidney stones is mediated by ALB and RDW." (PMID 40729360, 2025). "Therefore, we analyzed the RDW, albumin, and RAR levels obtained from the National Health and Nutrition Examination Survey (NHANES) to investigate the association between RAR levels and the prevalence of kidney stones." (PMID 39570091, 2024). "Moreover, evidence suggests that high‐protein diets, while elevating serum albumin, may specifically contribute to the development of kidney stones and other kidney diseases." (PMID 39570091, 2024). "In this study, the death cause was attributed to the diuretic property of the solution that may alter the glomerular filtration ratio and may lead to an increase in the uric acid level, serum albumin and deposition of urate crystals in soft tissue and kidney stones." (PMID 36139349, 2022). "Both uromodulin and albumin, the two conditioning film components identified as part of the encrusted areas, are known to bind calcium, raising the possibility that calcium-based crystals commonly present in urine of kidney stone patients are retained on the device surface by the components." (PMID 32962019, 2020). "This study aimed to reveal the relationship between the albumin-bilirubin (ALBI) score and kidney stones in adult patients with T2DM." (PMID 40386229, 2025). "We conducted mediation analyses to explore the mediating roles of ALB and RDW in the relationship between IR and kidney stones." (PMID 40729360, 2025). "We evaluated the albumin-corrected calcemia, calciuria, PTH, 25(OH)D level, serum phosphate, bone mineral density, and major clinical symptoms (fracture, nephrolithiasis)." (PMID 39040613, 2024). "Conversely, HDL-c, albumin, and impaired kidney function (characterized by elevated SUA, Scr, BUN, and reduced eGFR), were evident in the kidney stone group (P < 0.05)." (PMID 39444452, 2024). "While urinary albumin-to-creatinine ratio (UACR) is a recognized marker for kidney disease, its relationship with kidney stones, especially within the normal UACR range, remains unclear." (PMID 40162309, 2025). "Given the established connection between oxidative stress and kidney stone formation, we hypothesize that ALB and RDW may serve as key mediators in the relationship between IR and kidney stones." (PMID 40729360, 2025). "The crude model revealed positive correlations between RDW, RAR, and kidney stone prevalence, as well as a negative correlation between albumin and kidney stone prevalence." (PMID 39570091, 2024).
kidney stones (continued). "The association between the red blood cell distribution width to albumin ratio (RAR) and kidney stone prevalence likely reflects the complex interplay of inflammation, oxidative stress, and metabolic disturbances, all of which are involved in kidney stone pathogenesis." (PMID 39570091, 2024). "Moreover, no related adverse (serious or non-serious) events, including nephrolithiasis (kidney stones), were observed in participants with serum calcidiol levels ≥ 100 nmol/L or with albumin-adjusted calcium levels > 2.55 mmol/L, at any of the time points." (PMID 32162241, 2020). "Furthermore, ALB and RDW may partially mediate the relationship between IR and kidney stones." (PMID 40729360, 2025). "Additionally, albumin serves as a vital non-enzymatic antioxidant with free radical scavenging properties, playing a central role in maintaining plasma redox status and influencing oxidative stress levels, which are factors in kidney stone formation." (PMID 39574520, 2024). "However, the relationship between the RDW to albumin ratio (RAR) and the prevalence of kidney stones in the general adult population is not yet established." (PMID 39570091, 2024).